DDX17 (DEAD-box helicase 17)
Diseases named in the same sentence as DDX17 in open-access papers (continued):
Sharing a sentence is not in itself a finding about the gene and the disease.
tumor (continued). "Meanwhile, dissociated DDX17 forms the DDX17/YAP/p300 complex, which enhances the transcription of tumor stem genes." (PMID 35992805, 2022). "For instance, H-Ras, CD44, PXN-AS1, macroH2A1, etc., are important tumor-related factors; therefore, the dysregulation of DDX5/DDX17 action is closely related to tumorigenesis and tumor progression." (PMID 35992805, 2022). "DDX17 is located at 22q12 in close proximity to the tumour suppressor MYH9, potentially explaining its recurrent deletion in tumour cell lines." (PMID 32463358, 2020). "Among them, only EMP1, PTPRG and DDX17 were downregulated in LUAD tissues by the analysis of TCGA database, suggesting their tumour suppression role." (PMID 31012177, 2019). "Unlike the adjacent nontumor tissues, DDX17 was highly expressed in tumor tissues compared in two independent cohorts and that it acts as an independent prognostic indicator for patients who have HCC." (PMID 39897048, 2025). "In addition, DDX17 influences the biogenesis of various miRNAs along with the YAP protein, the downstream target of the tumor-suppressive Hippo signaling pathway in cancer." (PMID 38689093, 2024). "DDX17 and DDX5 may play a critical role in tumor cell migration by simultaneously regulating the transcriptional activity and AS of NFAT5 in HeLa cells." (PMID 36164607, 2022). "DDX17 is also involved in the splicing of CD44, which is an extremely broad cell surface transmembrane glycoprotein and is mainly involved in the adhesion of tumor cells to host cells and the host matrix." (PMID 35992805, 2022). "Although there was no significance between DDX17 expression and tumor size and M stage, DDX17 was correlated to tumor stage and lymphatic metastasis." (PMID 31653828, 2019). "Moreover, we confirmed that silencing Ddx17 could increase surface MHC-I and OVA antigen expression of Map3k1-mut tumor cells, as measured by both immunofluorescence and flow cytometry, and thus enhanced the activation of CD8+ T cells in the coculture system." (PMID 39531335, 2024). "Once DDX5/DDX17 expression or DDX5/DDX17-related posttranslational modification is dysregulated, the cellular signaling network collapses or becomes abnormal, which leads to the acquisition of many pathological states, including those related to tumorigenesis and tumor development." (PMID 35992805, 2022). "In addition, further OS analysis was performed according to tumor stage, and results manifested that patients who were in stage I–II or stage III–IV, with higher DDX17 expression had worse outcome than those with lower DDX17 expression." (PMID 31653828, 2019). "Therefore, we assumed that non-significance between DDX17 and tumor size or distant metastasis was probably due to lack of large samples, which requires further research to validate." (PMID 31653828, 2019). "Interestingly, DDX5, but not DDX17, affect key cellular pathways, including upregulation of AR in PCa and induction of epithelial-mesenchymal transition (EMT), a feature that is associated with tumor invasion capabilities." (PMID 31164793, 2019).
digestive system tumors (2 papers, 2012 to 2025). "Collectively, DDX17 expression was significantly elevated in multiple digestive system tumors and positively correlated with poor survival." (PMID 39897048, 2025).
metabolic disorders (1 paper, 2024). "Moreover, we demonstrated that DDX17 may promote the activation of M1 macrophages and inhibit the activation of M2 macrophages by causing the metabolic disorders." (PMID 38303609, 2024).
DDX17 also shares sentences with these, for which no sentence is quoted: Fever (4 papers); head and neck squamous cell carcinoma (3); adult T-cell leukemia (1); Alzheimer disease (1); bacterial infection (1); cardiac hypertrophy (1); cervical tumor (1); chronic heart failure (1); clear-cell renal cell carcinoma (1); embryonic carcinoma (1); glioblastoma (1); hematological disorders (1); Hepatic steatosis (1); in liposarcoma (1); Infertility (1); interstitial nephritis (1); kidney failure (1); liver fibrosis (1); megalencephalic leukoencephalopathy (1); microtia (1); Myocardial fibrosis (1); myocardial ischemia (1); myotonic dystrophy (1); nephritis (1); nephrosis (1); neurodegenerative disease (1); pancreatic ductal adenocarcinoma (1); preeclampsia (1); small intestine (1); small intestine tumors (1).
A further 4 diseases each share a sentence with DDX17 in 1 paper.